CDKN2A (cyclin dependent kinase inhibitor 2A)
Diseases named in the same sentence as CDKN2A in open-access papers (continued):
Sharing a sentence is not in itself a finding about the gene and the disease.
cutaneous melanoma (72 papers, 2004 to 2026). A primary melanoma arising from atypical melanocytes in the skin. "The most commonly mutated genes were TERT, BRAF, NRAS, and CDKN2A, consistent with known patterns of mutations in cutaneous melanoma." (PMID 39422848, 2025). "Inherited PVs in the CDKN2A tumor suppressor gene are among the strongest risk factors for cutaneous melanoma." (PMID 36901733, 2023). "Mutations of cell cycle regulators CDKN2A and CDKs were less common in acral melanoma compared with cutaneous melanoma." (PMID 37239381, 2023). "Other mutations and genetic alterations are known to be present in cutaneous melanoma, such as CDKN2A mutation, PTEN loss, and amplification of MITF, EGFR, CCDN1, cMET, and cKIT." (PMID 35682684, 2022). "Inherited pathogenic variants (PVs) in the CDKN2A tumor suppressor gene are among the strongest risk factors for cutaneous melanoma." (PMID 34069952, 2021). "Recently, a new CDKN2A pathogenic variant, p.D84V (c.251A > T) has been described in an Italian study which included patients with multiple primary cutaneous melanomas or with primary cutaneous melanoma associated with family history of melanoma and/or PDAC." (PMID 28670351, 2017). "Inactivating mutations in the CDKN2A gene which encodes for p16INK4a tumour suppressor protein, pose a high risk for development of cutaneous melanoma." (PMID 26850723, 2016). "Both BRAF and CDKN2A mutations in cutaneous melanoma cells are characteristic of indirect UV-induced oxidative damage." (PMID 26850723, 2016). "The higher frequency of multiple melanomas in individuals with a familial form of cutaneous melanoma is an unquestionable fact, widely reported in the literature and intimately related with the presence of mutations in the CDKN2A gene." (PMID 25893138, 2014). "Notably, a number of down-regulating functional variants in CDKN2A had elevated allele frequencies in multiple cancers, including skin cutaneous melanoma (labeled as SKCM or MELA) which is associated with CDKN2A mutations." (PMID 38637555, 2024). "Notably, CDKN2A has also been identified as a canonical driver in cutaneous melanoma via analysis of somatic mutations." (PMID 38758740, 2024). "Germline mutations in the CDKN2A strongly predispose to cutaneous melanoma." (PMID 36845707, 2023). "Locus CDKN2A is the most frequently affected gene by germ-line mutations in cutaneous melanoma." (PMID 36613518, 2022). "Over 75% of cutaneous melanoma metastases have lost one or both alleles of CDKN2A." (PMID 32850962, 2020). "Germline mutations in the CDKN2A (p16) gene may result in cutaneous melanoma." (PMID 32571290, 2020). "Despite the high incidence of CDKN2A mutations, the number of patients in our cohort was limited, so we did not investigate prognostic features, but instead we focused on the interplay between germline and somatic variants in the key genetic drivers of cutaneous melanoma." (PMID 29464027, 2018). "The genes most recurrently affected by BA-SVs in cutaneous melanomas were CDKN2A and CDKN2B, with the majority being deletion events." (PMID 38758740, 2024). "Complete loss of staining in p16 indicates biallelic or homozygotic inactivation of the CDKN2A gene that corresponds to the late molecular event in the oncogenesis in advanced cutaneous melanomas." (PMID 38247727, 2024). "Data taken from DepMap using cutaneous melanoma cell lines also indicated increased dependency on several nucleotide metabolism genes based on CDKN2A expression." (PMID 38626341, 2024).
cutaneous melanoma (continued). "Chromosomal instability also characterizes skin melanomas resulting in the frequent amplification of CCND1 and MITF and loss of CDKN2A and PTEN." (PMID 36980598, 2023). "In the majority of the most common histological forms, cutaneous malignant melanoma is a genetically well-defined tumor with clear driver and suppressor profiles dominated by BRAF and CDKN2A mutations." (PMID 36980598, 2023). "Of interest, a cutaneous case (CRUKP1842) had a pathogenic germline mutation in CDKN2A and had the lowest TMB of the sun-exposed cutaneous melanomas." (PMID 36977461, 2023). "After excluding patients positive for CDKN2A/CDK4 pathogenic variants and those affected by non-cutaneous melanomas, our study cohort comprised 984 cutaneous melanoma patients, 22 MITF+ and 962 MITF−." (PMID 32054529, 2020). "On the other hand, hotspot mutations in the genes BRAF and NRAS, in combination with homozygous deletions of the gene CDKN2A, were frequently found in cutaneous melanoma." (PMID 32825510, 2020). "Germline mutations in CDKN2A and/or red hair color variants in MC1R genes are associated with an increased susceptibility to develop cutaneous melanoma or non melanoma skin cancer." (PMID 24742402, 2014). "Similarly, CDKN2A DEL increased the risk of distant metastasis in multiple cancers, including HNSC, KIRC, PAAD, skin cutaneous melanoma (SKCM), and stomach adenocarcinoma (STAD) in TCGA cohort." (PMID 38822443, 2024). "Cutaneous melanoma and BC share common mutations at susceptibility genes, like BRCA2 and CDKN2A." (PMID 32497148, 2020). "CDKN2A is also highly mutated in rarer subtypes of cutaneous melanoma and in non-cutaneous melanoma." (PMID 33076392, 2020). "Identical mutations in both genes were present in the primary cutaneous melanoma and the lung mass – in absence of a germline CDKN2A mutation – confirming that the lung mass was a late metastasis of the cutaneous melanoma." (PMID 25593912, 2014). "For instance, the majority of cutaneous melanoma harbor mutations of B-Raf proto-oncogene, serine/threonine kinase (BRAF), NRAS proto-oncogene, GTPase (NRAS) and neurofibromin 1 (NF1) as well as loss of cyclin dependent kinase inhibitor 2A (CDKN2A) encoding P16NK4a." (PMID 34830903, 2021).
cutaneous melanoma (continued). "Many of them were previously appreciated in the genome of skin melanomas (e.g., MITF, NOTCH2, PD-L1 and JAK2 amplifications, or CDKN2A deletions); however, the CNAs in genomic locations harboring PAX5, ETS1, BCL7, RAD51, APAF1, FOXO3 and CTNNA1 are novel." (PMID 33779796, 2021). "The p-values of ACC, KIRC, LIHC, MESO, PARD, SKCM (Skin Cutaneous Melanoma) and UCEC tumors were 0.003, 0.028, 0.004, 0.007, 0.001, 0.037, and 0.001, respectively, due to the high expression level of CDKN2A in the progression-free interval (PFI)." (PMID 35004697, 2021). "However, loss of CDKN2A alone does not robustly generate cutaneous melanoma." (PMID 32504051, 2020). "Previous studies have shown that CDKN2A germline PVs does not affect the prevalence of somatic BRAF and NRAS mutations in cutaneous melanomas, and that familial and sporadic melanomas share similar gene expression signatures." (PMID 34069952, 2021). "However, the genetic alterations that give rise to uveal melanoma (i.e., GNAQ) differ from those in cutaneous melanoma (i.e., BRAF, CDKN2A, CDK4), suggesting that different pathways may be involved in their progression." (PMID 35525274, 2022). "However, the relationship between UVR and cutaneous melanoma is not yet fully understood, given the absence of a UV DNA damage signature in genes relevant to cutaneous melanoma such as BRAF, NRAS, or CDKN2A (cyclin dependent kinase inhibitor 2A)." (PMID 35682684, 2022).
squamous cell carcinoma (72 papers, 2001 to 2026). A carcinoma arising from squamous epithelial cells. "In a Chinese study, the authors reported that methylation, and therefore decreased CDKN2A expression, were associated with the lymph node metastasis in squamous cell carcinomas of the buccal mucosa." (PMID 39590385, 2024). "In squamous cell carcinoma, the occurrences of CDKN2A (27%) and PTEN (17%) mutations become more frequent compared to other cancer subtypes, while in small cell carcinoma, RB1 mutations become more prevalent (40%)." (PMID 28373672, 2017). "Promoter hypermethylation has indeed been shown to turn off CDKN2A locus in cancer but CDKN2A hypermethylation was linked to heavy smoking and squamous cell cancer which represents a different subgroup of tumors." (PMID 18549475, 2008). "Both MBC and squamous cell carcinoma are associated with inactivation of CDKN2A." (PMID 39399685, 2024). "Interestingly, deletion of CDKN2A (p16INK4a) was strongly associated with a favourable OS in our cohort, which contrasts other reports about CDKN2A loss and a poor prognosis, including other squamous cell carcinomas." (PMID 33506581, 2021). "There were no discernible copy number alterations in the actinic keratosis or squamous cell carcinoma of the example case, though there was allelic imbalance of chromosomal arm 9p, affecting the CDKN2A gene." (PMID 41309580, 2025). "Mutations in other genes, such as CDKN2A and ARID2, were rare in normal skin but common in squamous cell carcinoma, implying that they undergo selection comparatively later in tumor evolution." (PMID 41309580, 2025). "In two cases of thymic carcinoma (both squamous cell carcinomas) with homozygous deletion of CDKN2A, mTAP expression was lost; in a lymphoepithelial carcinoma with homozygous deletion of CDKN2A, mTAP was expressed." (PMID 35565429, 2022). "In cases in which we had results of CDKN2A FISH studies and mTAP IHC, we identified a concordant homozygous deletion of CDKN2A and loss of expression of mTAP in two squamous cell carcinomas." (PMID 35565429, 2022). "In four carcinomas with homozygous deletion of CDKN2A, mTAP expression was lost in two squamous cell carcinomas and in a subset of tumor cells of an adenocarcinoma and was preserved in a lymphoepithelial carcinoma." (PMID 35565429, 2022). "The frequency of CDKN2A deletion in squamous cell carcinoma combined with other components was significantly higher than that in pure squamous cell carcinoma (66.7% vs. 19.9%, P = 0.026)." (PMID 27145277, 2016). "The gene copy ratio of MYC and CDKN2A in the same pattern has a prognostic value in squamous cell carcinoma of the head and neck." (PMID 24675718, 2014). "Notably, methylation of CDKN2A was detected in 100% of sputum samples from individuals who later developed squamous cell carcinoma, up to three years before diagnosis." (PMID 41303058, 2025).
squamous cell carcinoma (continued). "Interestingly, in one of our thymic squamous cell carcinomas, NGS revealed CDKN2A/B loss despite normal CDKN2A FISH results and expressed mTAP." (PMID 35565429, 2022). "In the squamous cell carcinoma, NGS identified CDKN2A/B loss." (PMID 35565429, 2022). "Similarly, in squamous cell carcinoma (SCC) TWIST is regulating BMI1 to cooperatively repress CDKN2A (p16INK4A) and promote tumor initiation capacities." (PMID 34459003, 2021). "Another in a growing number of examples is the aberrant methylation of the p16INK4a/CDKN2A promoter which has been shown to be present in both human squamous cell carcinomas and their precursor lesions, indicating that it occurs in the early stages of neoplastic transformation." (PMID 25949794, 2014). "Tumor epithelial clusters expressed canonical squamous carcinoma markers such as CLDN1, LAMB3, TP63, CDKN2A, EPCAM, and SERPINB2, validating their malignant identity, while stromal and immune subsets displayed expected transcriptional programs." (PMID 41510303, 2025). "Although cyclin-dependent kinase inhibitor 2A (CDKN2A) is frequently altered or deleted in a wide range of cancers and is known to be an important tumor suppressor gene, a study suggested that CDKN2A plays a key role in the formation and progression of larynx squamous cell carcinoma." (PMID 36186479, 2022).